IL7 (interleukin 7)
Diseases named in the same sentence as IL7 in open-access papers (continued):
Sharing a sentence is not in itself a finding about the gene and the disease.
tumor (continued). "IL-7 has shown promising results in clinical trials with the combination therapy of IL-7 with lysosomal viruses used to enhance anti-tumour effects." (PMID 38675377, 2024). "Studies have shown that IL-7 can increase the number and function of tumour-infiltrating lymphocytes and improve the efficacy of immune checkpoint inhibitors such as PD-1 and PD-L1 antibodies." (PMID 38675377, 2024). "The combination of IL-7 with antibodies has also shown promising anti-tumour effects in recent studies." (PMID 38675377, 2024). "In vitro, IL-7 activation promotes tumor cell mesenchymal switch, movement, and invasion via STAT5, JAK, and extracellular signal-regulated kinase (ERK) pathways, promoting epithelial–mesenchymal transition (EMT) and metastasis." (PMID 38745115, 2024). "CXCL13 and IL-7 interaction recruits LTi expressing lymphotoxin- α1β2 (LT- α1β2), which binds to the LT-βR on tumor stromal cells." (PMID 38333212, 2024). "Our study demonstrated that IL-7 affects monocyte recruitment to tumor sites and the induction of pro-inflammatory APCs." (PMID 38424167, 2024). "Since the murine cytokine IL-12/IL-7/IFN-α mRNA triplet exhibited significant anti-tumor efficacy in syngeneic mouse models, we generated a human cytokine mRNA triplet for clinical translation." (PMID 39290693, 2024). "IL-7 would be expected to maintain T-cell stemness and, as a consequence, promote the cytotoxicity of B7–H3 CAR-T/IL-7 cells against tumor cells." (PMID 39093440, 2024). "The data in this figure explicitly demonstrate the superior performance of C5/IL7-CAR-T cells in terms of numbers at the tumor site, cytokine release, and survival in a murine model." (PMID 39450160, 2024). "IL-7 has shown strong anti-tumour activity as a monotherapy and it can also be combined with other drugs to enhance anti-tumour activity." (PMID 38675377, 2024). "In mice receiving only carbo/pax chemotherapy, strong positive correlations with tumor burden were found for IL-7 (r = 0.8734, p = 0.0230), IL-10 (r = 0.8912, p = 0.0171), and CXCL10 (IP-10) (r = 0.9433, p = 0.0047)." (PMID 39623404, 2024). "Given its potent biological functions, IL-7 is considered to have the potential to be widely used in the field of anti-tumour immunotherapy." (PMID 38675377, 2024). "T cells and NK cells are cytotoxic cells that are essential for tumor eradication and are the primary responders to cytokines IL-12, IL-7, and IFN-α." (PMID 39290693, 2024). "The exact function of Interleukin-7 (IL-7) in controlling tumor cell autophagy, lymphangiogenesis, growth, and cell death is not completely clear; studies are centered on mTOR and Beclin-1." (PMID 39650649, 2024). "IL-7 can increase cytotoxicity and enhance the anti-tumor effect of CAR-T cells by decreasing immune checkpoint expression in CAR-T cells." (PMID 39093440, 2024). "Ex vivo tumor cultures and patient-derived xenograft models demonstrated that human IL-7 upregulated pro-inflammatory cytokines and activated infiltrating CD4+ and CD8+ T cells in a dose-dependent manner." (PMID 38424167, 2024). "Whole tumor cell-based vaccines expressing IL7 demonstrated vigorous preventative and therapeutical outcomes in murine models, inhibiting tumorigenesis and extending survival time." (PMID 38289597, 2024). "Due to the substantial anti-tumour activity displayed by IL-7 and CAR-T cells in haematological malignancies, their combination has been incorporated into clinical trials for diverse cancer immunotherapies." (PMID 38675377, 2024). "Consistently, 3:1:1 cytokine mRNA triplet conferred better anti-tumor efficacy, compared with the same total dose of IL-12 singlet, IL-12/IL-7 doublet, or IL-12/IFN-α doublet, in syngeneic B16F10 mouse model." (PMID 39290693, 2024). "The human cDNA of the cytokine IL-7, which can promote T cell survival, was encoded in a plasmid (pcDNA3.1-IL-7) and injected once i.t. followed by electric pulses in a TM40D mouse graft model of BC five days after tumor implantation." (PMID 38803496, 2024).
tumor (continued). "Like our results, that study showed the addition of RT allowed for substantially increased tumor reduction compared to IL7 alone." (PMID 38554147, 2024). "Induction of cancer cell migration, epithelial-mesenchymal transition, and tumor growth by IL-7 has been demonstrated by in vitro and in vivo studies." (PMID 38424167, 2024). "PI3K/Akt pathway was suggested to coordinate the upregulation of cytokines, such as IL6 and IL7 in tumor microenvironment during HCC recurrence." (PMID 38840185, 2024). "The titles of these publications were first reviewed to exclude articles with high expressions of IL-7 in tumours and the promotion of tumour growth." (PMID 38675377, 2024). "Similar to the mEER model, the RT + IL7 cohort had reduced tumor growth and prolonged survival outcomes compared to the other groups." (PMID 38554147, 2024). "The construction of a lysosomal adenovirus Ad5/3-E2F-d24-hIL-7 expressing IL-7 targets the tumour microenvironment for high expressions, overcoming systemic delivery problems and improving therapeutic efficacy." (PMID 38675377, 2024). "In breast tumor-bearing mice, type I IFN directly suppresses the activity of tumor-infiltrating γδ17 T cells, while indirect inhibition of γδ17 T cell-activating factor IL-7 reduces IL-17A secretion through two pathways, thereby impeding tumor progression." (PMID 39253082, 2024). "Specifically, the complex formed by IL-7 with IL-7R-Fc has been shown to induce an anti-tumour response by increasing the infiltration of T cells into tumours through the CXCR3 chemokine signalling pathway." (PMID 38675377, 2024). "The first report on the administration of recombinant human IL-7 (rhIL-7) to tumor patients was published in melanoma in 2006." (PMID 38424167, 2024). "The B7–H3 CAR-T/IL-7 therapy showed enhanced cytotoxicity and prolonged duration of action against tumor cells." (PMID 39093440, 2024). "The combination of IL-7 with DDP induces NSCLC tumour regression while reducing ABCG2 levels in tumour tissue." (PMID 38675377, 2024). "IL-7 plays a crucial and multifaceted role in the tumour microenvironment, selectively influencing the development of naïve and memory T cells while avoiding the stimulation of immunosuppressive Tregs." (PMID 38675377, 2024). "Our data show that IL7 in conjunction with RT can be used to control tumor growth in both HPV+ and HPV− preclinical models of HNSCC." (PMID 38554147, 2024). "Collectively, these data confirm that dex-mediated IL-7Rα upregulation on CAR T cells increases their responsiveness to IL-7, which allows for CAR T cells to have improved anti-tumor activity in the presence of IL-7." (PMID 38140726, 2024). "In this study, we evaluated the effects of several common cytokines in combination with SINV and found that arming either IL-7 or IL-12 increased the tumor-killing efficiency of SINV." (PMID 37835433, 2023). "The most intensively studied IL-7R agonist now in development is the PK-enhanced IL-7 efineptakin alfa, previously shown to suppress tumor growth in preclinical murine tumor models, both as monotherapy and in combination with a PD-1 CPI." (PMID 37874823, 2023). "In comparison to IL-15, IL-7 promotes the expansion of naïve T cells and leads to a more potent tumor-killing response." (PMID 37064017, 2023). "Other studies have found that in a patient with late-stage HCC, anti-GPC3 IL-7/CCL19 CAR-T therapy resulted in complete tumor disappearance 30 days post-intra-tumor injection." (PMID 37081982, 2023). "IL7 is an attractive candidate to enhance the anti-tumor response of CAR T cells due to several key impacts on T cell biology." (PMID 36817432, 2023). "IL-7–CBD provided prosurvival signals mediated by STAT5 activity to tumor-resident T cells, while CBD–IL-12 provided immune-activating signals mediated by STAT4 activation." (PMID 38019919, 2023).
tumor (continued). "Treatment with anti‐GM2 IL‐7/CCL19‐producing CAR‐T cells induced complete tumor regression along with an abundant T cell infiltration into the solid tumor tissue and long‐term memory responses, without any detectable adverse events." (PMID 37031457, 2023). "Conversely, other studies have indicated that IL-7 can activate the expression of T cells, macrophages, DC cells, and other immune cells, exerting an anti-tumor effect." (PMID 37910571, 2023). "Anti-IL-6 treatment alone increased the expression of stimulatory cytokines (IL-7 and IL-15) in MDSCs compared to the tumor-bearing control." (PMID 37108179, 2023). "In a phase II study, recombinant glycosylated human IL-7 (CYT107) combined with vaccine therapy treatment stopped tumor growth in patients with castration-resistant prostate cancer (NCT01881867)." (PMID 36936961, 2023). "Another engineering method is the incorporation of cytokine armoring genes, which leads to the production of cytokines required for T cell growth, including IL-15, IL-2, IL-7, IL-12, and IL-21, hence strengthening tumor-killing abilities." (PMID 37064017, 2023). "The use of an oncolytic adenovirus loaded with interleukin 7 has already shown promising results in clinical settings and increases tumor-infiltrating lymphocytes." (PMID 37443821, 2023). "In the context of HNSC, implementation of cytokine-based therapy with IL-2, IL-7, and IL-15 has demonstrated the ability to augment T cell activation, expansion, and anti-tumor effector function in patients." (PMID 37926766, 2023). "To date, a variety of myokines has been identified, including main driver mediators of an anti-tumoral tumor microenvironment such as the interleukins (IL) IL-7, IL-15, tumor necrosis factor (TNF) and interferon-gamma (INF-γ)." (PMID 37760634, 2023). "In combination with CCL21, IL-7 improved the anti-tumor activity of CLDN18.2-specific CAR T-cells in a syngeneic mouse model without lymphodepletion." (PMID 38201551, 2023). "Genetic modification of tumor antigen‐specific T cell receptor (TCR)‐T cells to produce IL‐7 and CCL19 also significantly enhanced the therapeutic efficacy in mouse models." (PMID 37031457, 2023). "Previous studies have shown that multiple cytokines, including IL-6 and IL-10, activate their receptors on GBM cells to promote tumor progression, whereas IL-7 reduces tumorigenicity and enhances the immune responses of CD8+ T cells." (PMID 37734869, 2023). "Lymphodepleting pre-conditioning using irradiation and/or chemotherapy can improve CAR T cell abundance by killing tumor cells, reducing competition for IL7 and IL15, and decreasing regulatory T cells." (PMID 36817432, 2023). "This can enhance CAR T therapy by killing tumor cells, removing IL-7 and IL-15 competition, making them more available to CAR T cells in the absence of endogenous lymphocytes, and, therefore, improving CAR T-cell proliferation and persistence." (PMID 37754534, 2023). "As an anti-tumor therapy, IL-7 can further the survival, growth and differentiation of T cells, maintain internal environmental stability and boost the development of memory precursors." (PMID 36936961, 2023). "Mechanistically, engineered IL-12 provided effector properties to T cells, while IL-7 prevented their exhaustion and boosted memory formation as assessed by tumor rechallenge experiments." (PMID 38019919, 2023). "As a result, it is difficult to modify IL-7 to design the next generation of engineered IL-7 cytokines against tumor growth." (PMID 36936961, 2023). "As in the previous study, IL-7/CCL19-producing human CAR-T cells exerted a significant inhibition of tumor growth and prolonged survival of treated mice." (PMID 35211124, 2022). "IL-7 has been reported to mitigate the induction of immune senescence of conventional T cells exposed to tumor cells." (PMID 36605214, 2022). "The early-stage clinical trials focus on designing tumor cell cancer vaccines expressing adjuvant molecular IL-7." (PMID 36389666, 2022).
tumor (continued). "Another reason for the increase of IL-7 serum levels at the start of tumor growth can be the counteraction of the immune system to the tumor, producing various cytokines, among them IL-7." (PMID 35794603, 2022). "Weekly bioluminescence analysis revealed that tumor development was delayed in Il7−/− mice compared with control Il7+/− and Il7+/+ mice in two independent experiments." (PMID 35156727, 2022). "In turn, robust metabolic activation was occurred in 28z/IL-7 CAR-T cells in the presence of tumor cells." (PMID 35869100, 2022). "Pre-clinical studies support the benefit of transgenic cytokines like IL15 and IL7 in augmenting the CAR T cell anti-tumor response; first clinical trials are evaluating safety and efficacy of the approach." (PMID 36700225, 2022). "IL-15, a type I cytokine together with IL-2, IL-4, IL-7, IL-9, and IL-21, promotes survival of T, B, and NK cells by binding to IL-15α, encoded by IL15RA, negatively regulating both carcinogenesis and tumor growth." (PMID 36432658, 2022). "IL-7 has a powerful immunomodulatory effect, which can directly or indirectly act on tumor cells and exert anti-tumor effects by enhancing tumor eradication or adaptive immunity." (PMID 36142322, 2022). "IL-7 has strong immunomodulatory effects, which can directly or indirectly act on tumor cells and exert anti-tumor effects by enhancing tumor eradication or adoptive immunity." (PMID 36142322, 2022). "In breast and lung cancer, IL-7 has also been shown to upregulate vascular endothelial growth factor, promoting angiogenesis and tumor growth." (PMID 36139575, 2022). "Several recent studies have revealed the superiority of IL-7/IL-15 over IL-2 in ex vivo expanding human naïve or tumor-experienced CD8+ T cells as well as CAR-T cells." (PMID 36394017, 2022). "Conversely, IL-7 also has potential pro-tumor effects via the activation of downstream JAK/STAT5 and PI3K–AKT pathways." (PMID 36142322, 2022). "The higher IL-7 serum level in BC patients can be explained by the production of different cytokines, including IL-7, by cancer cells, but the discontinuing increase of IL-7 serum levels during tumor growth and disease progression is controversial." (PMID 35794603, 2022). "In another phase I/II clinical trial, Wittig and colleagues cotransfected IL-7 and granulocyte-macrophage colony-stimulating factor (GM-CSF) genes in autologous tumor cells as a therapeutic vaccine to immunize patients with progressive metastatic carcinoma." (PMID 36389666, 2022). "In Section 3.2, the tumor-promoting effects of IL-7 and IL-7Rα and how they contribute to carcinogenesis have been described in detail." (PMID 36142322, 2022). "At least 1x106 IL-7-cotransfected tumor cells were administrated subcutaneously in cancer patients with a minimum of four injections." (PMID 36389666, 2022). "28z/IL-7-CAR-T cells were as effective as conventional CAR-T cells (28z-CAR-T cells) to mediate tumor cell lysis." (PMID 35869100, 2022). "CXCR3 ligands have been suggested to play an essential role in IL-7/IL-7Rα-Fc-mediated anti-tumor activity in lung cancer studies." (PMID 36479091, 2022). "The data from this study will contribute to the discussion about the role of IL-7 in the development of BC, in particular, to evaluate the possibility of using IL-7 as a tumor biomarker and prognostic indicator in BC." (PMID 35794603, 2022). "Since direct injection of IL-7 as an adjuvant has been proven to be safe and effective, IL-7-cotransfected tumor cell vaccine, which is labor- and time-consuming in manufacturing, seems to be unsuitable and inconvenient in clinical practice." (PMID 36389666, 2022). "To further stress the in vitro system, we set up a second tumor re-challenge assay in which CAR T cells were expanded for 10 days in the presence of IL-7 and IL15, co-cultured with Namalwa cells at E:T ratio of 1:1 and challenged every day." (PMID 36275777, 2022).
tumor (continued). "To this aim, we isolated TILs from MC38‐derived tumor masses grown in control or Drp1‐cKO mice (treated with anti‐IgG or anti‐PD‐1) and let them expand in vitro in the presence of IL‐2, IL‐7 and IL‐15 cytokines." (PMID 34535949, 2022). "The role of IL-7 in tumor apoptosis, migration, proliferation and lymphangiogenesis has been reported." (PMID 35778432, 2022). "In support of this, administration of the hematopoietic growth factor, IL-7, caused increased CXCR3 expression on tumor-associated T cells and immune cell infiltration and decreased tumor burden." (PMID 36164329, 2022). "It is reported that IL-7 took anti-tumor effect in prostate cancer, glioma, melanoma, leukemia, and lymphoma." (PMID 35778432, 2022). "The combination therapy of oHSV2-IL12, -IL15, GM-CSF, -PD1v, and IL7 × CCL19 exhibited the highest tumor inhibition efficacy compared with the treatment of single OV or two OVs combination." (PMID 35459242, 2022). "In a phase I/II clinical trial (NCT00923351), recombinant human IL-7 was administered to pediatric sarcoma patients on days 0, 14 ± 7 d, 28 ± 7 d, and 42 ± 7 d after receiving autologous tumor lysate-pulsed DCs vaccination." (PMID 36389666, 2022). "When MPM and other neoplasia were combined into a malignant group (n = 188), IL‐7 levels still appeared to be higher in the malignant compared to the BPE group, but the difference was not significant." (PMID 36054746, 2022). "The effects of recombinant human IL-7 as an adjuvant in augmenting the number of tumor-infiltrating T cells, specific antitumor immune responses, and survival time of tumor-bearing models also have been revealed in other published studies." (PMID 36389666, 2022). "In the early stage, several clinical trials focus on the development of IL-7 gene-modified tumor cells as a cancer vaccine for patients with advanced malignant diseases." (PMID 36389666, 2022). "Patients received at least four injections of 1x106 autologous tumor cells transfected with the IL-7 gene/s.c." (PMID 36389666, 2022). "IL7 co-expressed with C-C motif chemokine ligand-19 (CCL19) or CCL21 produced an improved T cell memory response along with increased chemotaxis to the tumor lesion and enhanced amplification." (PMID 36700225, 2022). "Neutralizing CXCL9, CXCL10, or IFN-γ reduces CXCR3-expressing activated T cells infiltrating tumors and abrogates IL-7/IL-7rα-Fc-mediated tumor growth inhibition." (PMID 36479091, 2022). "When Comparing the CAR-T cells in the presence or absence of tumor cells, we noticed that OPA1 and CPT1 were the only two markers downregulated in 28z/IL-7-CAR-T cells in the presence of tumor cells." (PMID 35869100, 2022). "The levels of CXCL13, ICAM-1, MCP-5, and IL-7 in the serum, and the levels of IL-15 and sFasL in the tumor tissue decreased significantly after rAd-mIL-28B treatment relative to rAd-EGFP." (PMID 35935577, 2022). "Amongst cell-extrinsic modulators, the chemokine CXCL12 and interleukin 7 (IL7) play a key role in promoting tumor growth." (PMID 35805156, 2022). "To investigate a possible IL‐7 dependency in vivo, we again took advantage of the Pax5Jak2‐Luc/+ tumor cell transplant system and injected freshly harvested tumor cells into Il7+/+, Il7+/−, or Il7−/− recipient mice." (PMID 35156727, 2022). "The IL-7 enhanced the proliferation and survival ability of T cells that infiltrated into tumor tissues, which reduced the inhibitory of tumor microenvironment." (PMID 35295709, 2022). "Whole-cell cancer vaccines expressing IL-7 showed robust prophylactic and therapeutic effects against cancers, preventing tumor occurrence or prolonging the survival time in mice models." (PMID 36389666, 2022). "The possibility of different reactions of IL-7 in different tumor models was described in the previous study." (PMID 35794603, 2022). "Our model essentially relies on i.v. engraftment of PBMC isolated from patients with high tumor burden associated to a weekly supply of IL2 and IL7 cytokines." (PMID 36230895, 2022).